PROM1 (prominin 1)
Diseases named in the same sentence as PROM1 in open-access papers (continued):
Sharing a sentence is not in itself a finding about the gene and the disease.
ovarian carcinoma (235 papers, 2008 to 2026). A malignant neoplasm originating from the surface ovarian epithelium. "In general, high PROM1 expression was associated with poor survival in mixed Ewing sarcoma and brain, esophageal, gastric, liver, and ovarian cancers." (PMID 31164716, 2020). "We observed that PROM1 was frequently overexpressed in esophageal, liver, and ovarian cancers and its expression was negatively associated with prognosis, whereas PROM2 overexpression was associated with poor overall survival in lung and ovarian cancers." (PMID 31164716, 2020). "Additionally, prominin-1 (prom-1), a cell surface biomarker known as an organizer of cellular membrane protrusions and a cell surface marker of cancer stem cells has been associated with ovarian cancer and other solid tumors." (PMID 34830322, 2021). "Although PROM1 serves as a prognostic marker in other cancers like liver and ovarian cancer, its specific functional implications within ccRCC require further investigation." (PMID 40650074, 2025). "Analysis of Oncomine data showed that PROM1 was upregulated in leukemia and esophageal, liver, and ovarian cancers, but downregulated in other cancer types, including kidney cancer." (PMID 31164716, 2020). "Based on this expression pattern, we performed a multivariate survival analysis of PROM1/PROM2 co-expression in ovarian cancer." (PMID 31164716, 2020). "In summary, a comprehensive analysis of survival data from a range of online resources, highlighted the oncogenic role of PROM1 in brain and ovarian cancers." (PMID 31164716, 2020). "For example, PROM1 upregulation has been reported in ovarian cancer and targeting this gene retards ovarian cancer development in an in vivo model." (PMID 31164716, 2020). "CD133 (prominin-1), a 5-transmembrane glycoprotein that is a putative marker for cancer stem cells (CSCs) in solid tumors including ovarian cancer, has been thought to define a subpopulation of tumor-initiating cells with enhanced resistance to platinum." (PMID 25399490, 2014). "Moreover, PROM1+ ovarian CSCs are highly tumorigenic, chemo-resistant, and metastatic and they promote the adhesion capabilities of the ovarian cancer metastatic niche." (PMID 31164716, 2020). "For example, PROM1 overexpression has been shown in esophageal and ovarian cancers." (PMID 31164716, 2020). "Other ovarian cancer stem cells (OCSCs), identified by surface markers CD44, Prominin 1 (PROM1, CD133), and Aldehyde Dehydrogenase 1 Family Member A1 (ALDH1A1), reportedly involved in EOC development, relapse, and chemoresistance." (PMID 35401749, 2022). "It is noted that exposure of ovarian cancer cells to lipoplatin decreased aldehyde dehydrogenase and prominin-1 (also known as CD133) expression, which are markers of ovarian cancer stem cells and decreased spheroid growth and cell migration." (PMID 30071606, 2018). "Thus, based on mRNA expression and clinical data from Oncomine and TCGA, we conclude that PROM1 has as an oncogenic role in brain, esophageal, ovarian, and gastric cancers and melanoma and PROM2 shows oncogenic behavior in lung and ovarian cancers." (PMID 31164716, 2020). "CD133/ Prominin-1 is an established and broadly accepted pro-neural GBM stem cell marker that is also shared with other cancer stem cells from melanoma, prostate, pancreatic, liver, colon, lung, and ovarian cancers." (PMID 27472461, 2016).
melanoma (211 papers, 2008 to 2025). A malignant, usually aggressive tumor composed of atypical, neoplastic melanocytes. "The expression of genes encoding Wnt inhibitors was observed to be upregulated when CD133 (Prominin-1 a cell surface molecule often associated with CSCs) was down regulated in melanoma cells." (PMID 27999207, 2017). "In melanoma cell lines from both mice and humans, Notch1 also induced CD133 expression by the binding of activated Notch1 to the Prom1/PROM1 promoter." (PMID 38532366, 2024). "It was shown that lymph node metastatic melanoma cells expressed prominin-1 (CD133), and exosomes derived from these cells were enriched in this protein." (PMID 36674479, 2023). "A transfer of prominin-1 from melanoma cells to bone marrow-derived stromal cells via exosomes was detected." (PMID 36674479, 2023). "For instance, EVs from melanoma cells were shown to carry high levels of prominin-1, which contributed to metastatic progression." (PMID 36979019, 2023). "Rappa and colleagues profiled FEMX-1 melanoma sEVs that were enriched for the pentaspan transmembrane protein prominin-1/CD133." (PMID 35804857, 2022). "Among CSC markers, CD133 (Prominin-1), a pentaspan membrane glycoprotein, has been considered as one of the most important surface markers for identification of melanoma stem cells." (PMID 36325671, 2022). "First, we confirmed a significant induction of stemness NANOG, POU5F1 and PROM1 in the melanoma sphere formation process, in both primary and secondary WT spheres." (PMID 32230715, 2020). "For example, exposure of mesenchymal stem cells (MSCs) to exosomes from Prominin-1-positive melanoma cells resulted in an increased invasiveness of the MSCs." (PMID 27941674, 2016). "Prominin-1 is a transmembrane protein marker of both neural stem cells and hematopoietic progenitor cells, and is present in both melanoma cell lines and melanoma patient samples." (PMID 27941674, 2016). "We previously reported that prominin-1 had a pro-metastatic role in melanoma cells and that microvesicles released from metastatic melanoma cells expressed high levels of prominin-1." (PMID 23767874, 2013). "PROM1 transcripts initiate at P6 in cancer tissues, CD133+ melanoma cells, adult tissues, and stem cell enriched populations, including CD133+ selected cells from four primary Ewing sarcoma samples for which stem cell behavior has been established." (PMID 24194746, 2013). "mRNA isolated from CD133+ cells derived from the melanoma cell line LM-MEL-34 was used to amplify the 5′ end of the PROM1 transcript with the help of a pair of forward primers targeted to a RACE adapter and the other pair of reverse primers specifically targeted to 5′ exon of PROM1." (PMID 24194746, 2013). "Prominin-1, a pentaspanning transmembrane protein originally identified as a surface marker of both neural and hematopoietic stem and progenitor cells, is expressed in both established melanoma cell lines and clinical specimens derived from melanoma patients." (PMID 23767874, 2013). "To determine PROM1 promoter utilization across diverse tissues at high resolution we analyzed CAGE tags obtained from CD133+ melanoma cell lines and an additional 72 samples grouped as cancer, normal adult tissues and developmental stages from the public FANTOM4 data set." (PMID 24194746, 2013). "Although stemness features have been attributed to melanoma, our evaluation of stemness genes (NANOG, POU5F1, PROM1 and SOX2), revealed a very low expression among the tested cells on 2D culture." (PMID 32230715, 2020). "Building on our previous finding of a pro-metastatic role of prominin-1 in melanoma, we have here isolated from in vitro serum-free cultures of FEMX-I melanoma prominin-1-expressing exosomes." (PMID 23767874, 2013). "CD133 (prominin-1) is one of the most important cancer stem cells (CSCs) that is widely expressed in the CSC subpopulation derived from a large variety of human malignancies, including melanoma." (PMID 38334632, 2024).
melanoma (continued). "Indeed, melanoma CSC can be identified because they display either undifferentiation or embryonic state markers, such as NGF receptor, Prominin-1 (CD133), Transcription Factor Sox2, Octamer-binding protein 4, and Homeobox protein NANOG (NANOG)." (PMID 31783660, 2019). "Short-term co-culture of melanoma cells and MSC resulted in heterologous prominin-1 transfer." (PMID 23767874, 2013). "Those cells are referred as tumor stem-like cells (TSLCs), and CD133 (also known as prominin-1 or AC133) has been considered as an important marker to enrich the stem-like population in tumors of various tissues, including those of the brain, prostate, pancreas, liver, colon, and skin for melanoma." (PMID 20167130, 2010).
liver cancer (203 papers, 2008 to 2026). An epithelial or non-epithelial malignant neoplasm that arises from the liver. "Understanding the mechanisms underlying how PROM1+ cells emerge and expand in AH mouse liver may reveal the potential pathogenic role of these cells in AH and liver cancer susceptibility." (PMID 33173221, 2020). "TIPRL accelerates liver cancer aggressiveness via the upregulation of the microtubule-associated protein light chain 3 (LC3), an autophagy marker, and CD133 (Prominin-1) expression." (PMID 34208132, 2021). "This study assessed the human TOR signaling regulator (TIPRL)/microtubule-associated light chain 3 (LC3)/prominin-1 (CD133)/cluster of differentiation 44 (CD44) as potential diagnostic and prognostic biomarkers for early liver cancer." (PMID 34208132, 2021). "Cell markers that identify liver cancer stem cell populations include prominin-1 (CD133+), CD44+, CD13+, epithelial cell adhesion molecule (EpCAM+), CD90+, oval cell marker antibody 6 (OV6+), and aldehyde dehydrogenase (ALDH+)." (PMID 33669204, 2021). "In liver cancer PROM1 was more strongly co-expressed with a larger number of genes, including CFTR, KRT7, ANXA3, TACSTD2, and FZD1." (PMID 31164716, 2020). "In our study, DDR1 was identified as a tumor driver gene in PROM1+ subpopulation relevant to both mouse and patient liver cancer." (PMID 33173221, 2020). "In normal mouse liver, a PROM1+CD49f+CD45– population accounts for ~ 0.1% which increases to 1.93% in diethyl nitrosamine (DEN)-liver cancer model." (PMID 33173221, 2020). "CD133/prominin-1, a pentaspan membrane glycoprotein, is an important cancer stem cell surface marker in various solid tumors, including liver cancer." (PMID 23097677, 2012). "Reminiscent of human liver cancers that express both lineages, we noted the upregulated expression of stemness markers such as Sox9, Sox4, Cd44, Prom1 and Cd24a in HepYF-M13 and HepYF-M14 cells compared to their expression in normal hepatocytes and H2.35 immortalized hepatocytes." (PMID 39051113, 2024). "Our findings suggest that DDR1 may at least in part facilitate a potential tumorigenic link of PROM1+ cells to liver cancer." (PMID 33173221, 2020). "Interestingly, the Oncomine database also showed low and high expression of PROM1 in liver cancer and sarcoma depending on the analysis." (PMID 31164716, 2020). "A strategy to selectively direct interventions to key driver genes such as DDR1 in PROM1+ TICs may be desired for the therapy for liver cancer." (PMID 33173221, 2020). "To ask whether the properties of tumor in transplant experiment is the same as the original cell line, we used qPCR to analyse the differentiation-related genes including Afp, Albumin and K19, as well as liver cancer stem cell-related genes such as Prom1, Thy-1, Nanog, and Anpep." (PMID 38956432, 2024).
brain tumor (179 papers, 2006 to 2025). "To highlight the possible role of quiescent PROM1+ cells in brain tumor we decided to develop an approach to visualize them first and then proceed to a further characterization." (PMID 35970913, 2022). "CD133, also known as Prominin-1, is a transmembrane glycoprotein that is expressed on neural precursor cells of postnatal cerebellum and several brain tumor cells." (PMID 27627801, 2016). "To characterize Prom1+ brain tumor cells, we co-immunostained sections of the tumors with neural and vascular specific markers and anti-ß-galactosidase monoclonal antibodies." (PMID 23637986, 2013). "CD133 (also known as Prominin 1) was identified as a surface marker of cancer stem cells in brain tumors." (PMID 19823589, 2009). "Moreover, genes previously identified in our BMIC gene signature as well as associated with brain tumor initiating cells (IMPDH2, PROM1) were also detected, independently confirming our previous findings and further supporting the validity of our strategy." (PMID 40601773, 2025). "Using the public database TCGA, we analyzed the expression of genes studied in the present study, including PRRX1, PROM1, and DNMT3A, to investigate possible correlations between the expression of these genes, the brain tumor grade, and patient prognosis." (PMID 34214250, 2022). "We observed that about half of qProm1 cells express also SOX2, suggesting the possible co-existence of two different quiescent populations, Prom1+/SOX2+ and Prom1+/SOX2-, as also observed in human brain tumor samples." (PMID 35970913, 2022). "A stem-cell marker now extensively used as a surface marker to identify and isolate cancer stem cells in malignant brain tumours, CD133 (a transmembrane protein also called prominin 1), has been subjected lately to much controversy." (PMID 23998913, 2013). "The cell surface marker CD133 (also known as prominin-1) is a five-domain transmembrane molecule, and has been identified as a putative CSC marker in various cancers, including brain tumors, prostate carcinoma and CRC." (PMID 23216926, 2012). "Despite the high PROM1 expression in BG01V APCs when cultured under adherent conditions, there is insufficient evidence to classify trisomic BG01V APCs as brain tumor-initiating cells." (PMID 20423517, 2010). "Interestingly, PROM1 and GLAST1 are also upregulated in brain cancer cells and correlate with poor prognosis, demonstrating the intricate relationship between NSCs and brain tumors." (PMID 38251863, 2024). "This is supported by previous studies calling for further investigation of intercellular communication between prominin-1 (CD133+) niches and adjacent blood vessels within GBM, with the view to design specific targeted treatments directed at brain tumor stem cells." (PMID 38258133, 2024). "Overall, we identified a population of malignant non-cycling PROM1+ cells (including quiescent cells), consistently present in pediatric brain tumors." (PMID 35970913, 2022). "The cell surface marker of CD133 also known as AC133 in humans or prominin-1 in rodents is a five domain transmembrane molecule with a molecular weight of 120 kDa that has been identified as a normal and putative CSC marker in several cancers, including brain tumors, prostate carcinoma and CRC." (PMID 33391379, 2021).
prostate carcinoma (155 papers, 2006 to 2025). A carcinoma that arises from epithelial cells of the prostate gland. "PROM1 encodes a transmembrane glycoprotein widely used as a stem cell marker, but its potential role in prostate cancer is unknown." (PMID 28052017, 2017). "For PROM1, a large number of positively correlated genes were detected in esophageal, pancreatic, liver, and prostate cancers." (PMID 31164716, 2020). "Prominin-1, also known as CD133, has been well documented to be a putative cancer stem cell surface marker in a number of tumors including prostate cancer." (PMID 26497689, 2015). "We observed cancer-specific promoter hypermethylation and downregulation of PROM1 (CD133) expression, which is consistent with reports of PROM1 downregulation in several malignancies, including prostate cancer." (PMID 28052017, 2017). "In particular, the expression of surface biomarkers CD44, prominin-1 (CD133), as well as Nestin, were frequently reviewed, next to the expression of aldehyde dehydrogenase 1 (ALDH1), which indicates chemoresistance and poor prognosis of e.g., prostate cancer patients." (PMID 35203471, 2022).
gastric cancer (125 papers, 2008 to 2025). A primary or metastatic malignant neoplasm involving the stomach. "Cell membrane surface markers, such as CD133 (a human glycoprotein encoded by the PROM1 gene), Lgr5 (a G-protein-coupled receptor rich in leucine repeats), and EpCAM (an epithelial cell adhesion factor), predominantly contribute to the development of gastric cancer." (PMID 38882596, 2024). "Recently, Prominin-1 (CD133) has been considered to be a CSC marker in many types of cancers, such as breast, colorectal, brain, prostate, pancreatic, and gastric cancers." (PMID 23049880, 2012).
osteosarcoma (85 papers, 2008 to 2025). A usually aggressive malignant bone-forming mesenchymal neoplasm, predominantly affecting adolescents and young adults. "For example, PROM1 may be a biomarker for the prediction of lung metastasis and poor prognosis in patients with osteosarcoma, in which the expression of this gene is considerably high." (PMID 31164716, 2020). "The PROM1 gene, also known as CD133+, is one of the principal markers of osteosarcoma cancer stem cells together with CD34, a marker of the undifferentiated state of the cells, and the ALDH1A1 genes." (PMID 27651797, 2016). "CD133/prominin-1, a cancer stem cell marker, SSEA4 (stage-specific embryonic antigen 4), a glycoprotein expressed early in embryonic development and in pluripotent stem cells, and SSEA1/CD15 (stage-specific embryonic antigen 1) have been identified in osteosarcoma cells." (PMID 28934267, 2017).